CCL2 (C-C motif chemokine ligand 2)
Diseases named in the same sentence as CCL2 in open-access papers (continued):
Sharing a sentence is not in itself a finding about the gene and the disease.
infection (continued). "The chemokines CCL2, CCL5, CXCL1 as well as CXCL10 are all important for recruiting immune cells to the site of infection, and by inhibiting their biological activity, P. gingivalis is able to modulate and diminish the level of infiltrating immune cells." (PMID 23841502, 2013). "The chemokines IP-10 (CXCL10), MCP-1 (CCL2) and RANTES as well as the cytokines IL-6, IL-1β IL-1Rα and IL-12 are similarly expressed early following infection and their levels correlate with viral loads." (PMID 23936572, 2013). "Those mRNAs for CCL2, CCL31, CCL4, CXCL10, CCR1 and CCR5 were significantly increased following infection in both experiments in at least one time-point and CCL5, CCR9 and CXCR4 mRNA were significantly altered in one of the experiments." (PMID 24083897, 2013). "Monocyte chemoattractant protein-1 (MCP-1 or CCL-2) is a member of the CC chemokine subfamily, known to recruit cells of the immune system to the peripheral tissues during infection, injury, and other inflammatory conditions." (PMID 24303210, 2013). "Addition of Bb induced up-regulation of transcript levels for all chemokines assessed, including CXCL1, CXCL2, CCL2, CCL3, CCL4, and CCL5 by MØs and DCs as early as 4h post-infection." (PMID 24367705, 2013). "CCL2, also known as monocyte chemotactic protein-1 (MCP-1), recruits monocytes, memory T cells and dendritic cells to sites of tissue injury, infection and inflammation." (PMID 23824597, 2013). "Protein levels of CCL2 and CXCL8 were measured in supernatants from infected macrophages harvested at 16 h post-infection by ELISAs." (PMID 23265239, 2013). "Rather, RTD-1 administration appeared to protect infected animals by reducing pulmonary inflammation and suppressing IL-1α, IL-1β, IL-6, IL-12, CXCL1 (KC), CCL2 (MCP-1), CCL3 (MIP-1α), and CCL5 (RANTES) 2–4 days post-infection." (PMID 23236475, 2012). "Airway levels of CXCL1, CCL2, CCL3, CCL5, IFNγ, IL-6, and TNFα were measured 3 and 6 days after infection." (PMID 22496659, 2012). "Systemic infection of mice with L. monocytogenes leads to recruitment of CCR2+ monocytes via CCL2, into the spleen where they differentiate into TNF- and inducible NO synthase (iNOS)-producing DCs that are essential for control of the infection." (PMID 22383883, 2012). "The expression of CCL chemokine ligands CCL2, CCL4 and CCL7 was significantly higher in cells infected with the mutant, relative to the cells infected with Mtb, immediately following infection at the 0 hr time-point." (PMID 22235255, 2012). "One study showed that infection of mice with L. major upregulated the gene expression of several chemokines (RANTES/CCL5, MIP-1α/CCL3, IP-10/CXCL10, and MCP-1/CCL2) in cells collected from the footpad and their draining lymph nodes." (PMID 22131998, 2012). "In vitro infection of immature dendritic cells (imDC) with DENV-2 led to induction of CCL11/Eotaxin, CCL2/MCP-1, CCL5/RANTES, CCL3/MIP-1α and CXCL10/IP-10." (PMID 22815692, 2012). "Consistent with previous studies and associated with the classical activation M1 phenotype, transcription of TNFα (up to 5), CXCL10 (IP10), CCL2 (MIP1α), and other chemotactic cytokines such as CCL3 (up to 6.8) and CCL4 was upregulated following infection." (PMID 22928052, 2012). "During the experimental infection of macaques with CHIKV, we observed an early induction of IFN-α, MCP-1/CCL-2, and IL-6, followed by the detection of MIP-1α/CCL-3 and MIP-1β/CCL-4, IFN-γ, and TNF-α." (PMID 22479654, 2012). "The list of genes with the greatest induction following Mtb:Δ-sigH infection at this time-point included CXCL1 (120-fold), PTGS2 (100-fold), CXCL6 (75-fold), CCL2 (53-fold), CXCL3 (40-fold), CXCL1 (43-fold) and CCL2 (38-fold) CCL5 (35-fold)." (PMID 22235255, 2012). "Inflammatory cytokines, such as IFNγ, interleukin (IL)-6 and TNFα, and the chemokines, CCL2 and CCL5, were highly upregulated in the respiratory tract after infection with 12500 EID50." (PMID 22496659, 2012).
infection (continued). "Under these conditions, we also observed an elevated expression of CCL2/MCP-1 that is known to be necessary for recruitment of monocytes, memory T cells, and dendritic cells to sites of tissue injury, infection, and inflammation." (PMID 23192004, 2012). "We confirmed the results found for CCL2 and CCL5 by ELISA and found higher concentrations of protein at 20 weeks of infection in lesions from TNFR1 KO mice." (PMID 22203861, 2012). "On the other hand, four days after infection, TLR3−/− mice showed significantly increased mRNA expression of IL-6, CCL2, CCL11 and IFN-λ." (PMID 21637773, 2011). "Twenty-four h after RV1B infection, CXCL1/KC, CXCL2/MIP-2, IL-6, CCL2/MCP-1 and IFN-γ expression in wild-type mice increased 3–5 fold." (PMID 21637773, 2011). "Disease associated with highly pathogenic influenza viruses and the clinical manifestations that ensue in humans can be mediated by the proinflammatory response (e.g., TNF-α, IL-6, CCL2, CCL3, and CXCL10) initiated by the host in response to infection." (PMID 21829352, 2011). "Transcript levels for various cytokines/chemokines (KC [CXCL1], MCP-1 [CCL2], MIP-1α, IFN-γ, IL-4, IL-5, IL-6 and IL-10) were determined in lungs of infected mice on days 1, 6 and 9 post-infection." (PMID 20661429, 2010). "We thus next examined the levels of TNF, IL-1β, IL-2, IL-6, IL-10, and MCP-1 (also known as CCL2) in human PBMC infected by CDC1551, HN878, and HN878 pks1-15::hyg 2 and 4 days post-MTb infection." (PMID 19568431, 2009). "In mice infected with the ΔsigC mutant, the levels of TNF-α, IL-1β, IL-6 and IFN-γ began to drop 14 days post infection and persisted throughout the study while a significant reduction in CCL-2 and CCL-5 levels was detected 70 days after infection." (PMID 18798983, 2008). "CCL2, CCL7, and CCL8, members of the chemokine family, recruit monocytes to sites of injury and infection." (PMID 16805906, 2006). "Pro-inflammatory TNFα, CCL2 and CXCL8 are important in maintaining a balance between recruitment of other macrophages and also T cells to restrict infection." (PMID 16001981, 2005). "Similarly, proinflammatory cytokines CCL2, CXCL10, and CCL5, etc., were markedly elevated in the infection group." (PMID 41090515, 2026). "Recruitment of TLR5‐dependent immune cells via the CCL2/CCR2 pathway is critical to the development of functional CD4+ T‐cell‐mediated immunity, which helps control bacterial colonization and decreases the degree of infection." (PMID 41457476, 2026). "I.t. administration of the BK channel activator NS1619 (0.66 mg/kg) at 0 and 24 h following LPS infection reversed LPS-induced total BALF cell counts and neutrophil infiltration into the alveolar space, CCL-2 secretion, cytosolic ROS production by BALF cells, and LIS parameters." (PMID 40830381, 2025). "Moreover, only S- and S/N-immunized animals had reduced levels of CCL2, CCL3, CCL4 and CXCL10 chemokines after the infection compared to the PBS group." (PMID 41306976, 2025). "Importantly, it is known that MCP-1/CCL2 can direct the migration and infiltration of monocytes at the site of injury and infection, and are also involved in proliferation of T cells, thus important to the immune response." (PMID 40004157, 2025). "In this regard, MCP-1, a.k.a., CCL2, is C-C motif chemokine family member that plays a central role in controlling macrophage, dendritic cell (but not neutrophils or eosinophils) and memory T-cell recruitment at sites of inflammation/infection." (PMID 41282243, 2025). "However, we found similar levels of focal NF-κB p65, CCL2 expression, and IBA1+ cells near parasites in the brain after infection with control or ∆gra15 parasites, indicating that these phenotypes occur in a GRA15-independent manner." (PMID 40492741, 2025).
infection (continued). "M1 macrophages have the ability to recruit granulocytes, NK cells, Th cells, and other macrophages to the site of infection through the secretion of inflammatory chemokines, including the monocyte chemoattractant protein 1 (MCP-1), CXCL10, CCL2, CCL5, CXCL8, and CXCL9." (PMID 40234407, 2025). "For example, although targeting the CCL2/CCR2 axis can reduce the infiltration of TAMs, it may inhibit the protective effect of macrophages in infection or tissue repair." (PMID 41445742, 2025). "Levels of IL-8, IL-6, and MCP-1 (CCL2) were not yet detectably higher in either infection or IL-17C treatment by 6h." (PMID 38704381, 2024). "In summary, infection with the H7N7 IAV subtype stimulated the secretion of pro-inflammatory cytokines and chemokines in a microglia-dependent manner, with a higher secretion of CCL2 and CCL5 as well as IFN-β in female-derived cultures." (PMID 39171200, 2024). "This indicates that monocyte chemoattractant protein 1 (CCL2) and its receptor are essential in this process, although CCR deficiency does not alter the course of infection." (PMID 38535571, 2024). "Although ccl2 expression was not responsive to either miR-126 knockdown or infection alone, infection of miR-126 knockdown embryos increased ccl2 expression compared with knockdown alone and M. marinum–infected only embryos." (PMID 38307625, 2024). "Similarly, we observed significant increases in IL-17, G-CSF, CXCL1, CCL2, CCL3, CCL4, and CCL11 production in 5-LO−/− mice, compared to C57BL/6 mice, at day 7 post-infection." (PMID 39082787, 2024). "Subgroup analyses revealed significantly higher MCP-1/CCL-2 levels in participants with severe Plasmodium infections compared to those with non-severe infections in the Asia subgroup but not in the Africa subgroup." (PMID 39567619, 2024). "We assessed mRNA levels of CCL2 and did not observe a demonstrable impact of either infection on CCL2 levels in the jejunum, while coinfected pigs had increased CCL2 mRNA levels in the ileum compared to control pigs." (PMID 39140728, 2024). "This viewpoint aligns with previous research suggesting that CCL2 plays a more foundational role in initiating neuropathophysiological impacts in the initial stages rather than in the later stages of infection." (PMID 38627350, 2024). "WT and HuR KO RAW264.7 cells were infected with 1 MOI HAZV and at 9 h post infection, the expression of Il6, Ifnb, Tnf, Cxcl10, Il10, Il12p40, Ccl2 and Tgfb relative to non-infected control cells and the copy number of S segment inside cells were measured." (PMID 39348382, 2024). "In addition, we also found that the expressions of CCL2, CXCL10 and IL-6 were significantly increased in the terminal stage of infection with RABV." (PMID 39273091, 2024). "In addition, several members of the chemokine family of GPCRs have been observed to be upregulated in Calu-3 cells upon infection, including, among others, CXCL10, CXCL11 and CCL2." (PMID 38786015, 2024). "We first ensured that the knockout of astrocyte-derived CCL2 did not affect immune cell frequencies in the brain or periphery in the absence of infection." (PMID 38206985, 2024). "The DEGs involved in cytokine signaling were upregulated following infection with RHDV2 and included inflammatory cytokines such as IL1α, IL-6, and IL-8, and chemokines such as CCL2, CXCL9, and CXCL11, which were significantly upregulated compared with the non-infected rabbits." (PMID 38675838, 2024). "When macrophages detect microbial products, they initiate the inflammation program, producing chemokines and cytokines (such as IFNS, CXCL1, CCL2, TNFA, CXCl2, IL1B) necessary for recruiting leucocytes and upregulating neutrophil-killing capacity to resolve the infection." (PMID 39298265, 2024). "However, at 30 days post-infection, TNF-α, IL-6, KC, CCL3, CCL2, CCL20, CXCL11, CCL11), CCL27, CXCL5, CXCL12 and CCL5 were all significantly higher in the BAL fluid of Duox1 KO compared to WT mice." (PMID 36936954, 2023).
infection (continued). "MCP-1/CCL2 is one of the key chemokines regulating the migration and infiltration of monocytes/macrophages, which are known cellular reservoirs of CHIKV in the later stages of infection and play an important role in prolonged inflammation." (PMID 37515166, 2023). "Infection of MDMs with non-opsonized bacilli induced, at least 10-fold, the synthesis of most tested cytokines except IL-15, IL-27, CCL2 and CCL7." (PMID 37781389, 2023). "However, after infection with the H7N7, vaccination resulted in significantly lower CCL2 (p = 0.003) and IFNγ (p = 0.01) levels in the lungs of young mice compared with unvaccinated infected mice." (PMID 37063291, 2023). "However, even given this limitation, clear trends were observed, with increases in the pro-inflammatory cytokines TNFα and IL-1β, the regulatory cytokine IL-1RA and the chemokines CCL2, CCL17 and CCL3 in the sputum post-infection." (PMID 37012228, 2023). "We used qPCR to analyze 12 host-related genes, including those with no significant fold change (IL12A), modest (e.g. TNF, LMO1, IL10, CCL2, IL1B) or high fold change, including CXCL8 which was among the 50 identified to be most significantly dysregulated in monocytes as a result of infection." (PMID 36747074, 2023). "tularensis LVS-infection; a significant upregulation of genes involved in RAS pathway including Ccl2, Nfkb, p38 Mapk, Ras, Stat1, Stat3 and Tnf-α; and an upregulated expression of IFN-γ pathway genes such as Bak, Bax, Ifit, Ifn-γ, Irf, Isg, Oas1, Psmb8, Ptpn2, Stat and Tap1." (PMID 37266014, 2023). "Furthermore, plasmatic levels of CCL2, CXCL8, MIG, and IP-10 were elevated in patients with VL without clinical signs and symptoms, identifying them as robust markers of asymptomatic infection and therapeutic efficacy." (PMID 37999614, 2023). "The increased secretion of the chemokine MCP-1 (CCL2) observed in macrophages infected with BCG Pasteur at 48 h p.i. but not with BCG Moreau, may be reflecting an increased immune response against infection with this strain." (PMID 37851722, 2023). "CCL2, which drives macrophage differentiation during inflammatory response is also locally expressed in inflamed lungs and helps recruit CCR2+ monocytes from the circulation during PR8 infection." (PMID 36845136, 2023). "While our data in infected mice suggest that inflammasome was the inflammation trigger, we show that early infection induces robust NF-κB activation that could drive the expression of chemokines such as CXCL1,9,10,11 or CCL2,3,4,5." (PMID 36851549, 2023). "Infection with virulent ASFV isolates often results in exacerbated immune responses, with increased levels of serum pro-inflammatory interleukins (IL-1α, IL-1β, IL-6), TNF and chemokines (CCL2, CCL5, CXCL10)." (PMID 36680273, 2023). "Knockout of CCL2 or its principal receptor, CCR2, slightly reduced macrophage infection in culture." (PMID 37085605, 2023). "Results showed that infection of virulent isolate Benin97/1 significantly increased expression not only of CCL2, but also of CCL3, CCL4 and CCL5, although the greatest fold increase was observed for CCL2." (PMID 36680273, 2023). "Increased mCD14 and sCD14 levels result in the delivery of LPS to TLR4 after infection with gram-negative bacteria, which further affects the secretion of CCL2 and enhances the migration of immune cells." (PMID 37445719, 2023). "A. actinomycetemcomitans infection of implants caused a significant increase in the systemic expression of IL-2, IL-3, IL-5, CCL-3/MIP1α, and CCL2/MCP-1 compared to tissue infections without implants." (PMID 35203495, 2022). "Acute inflammatory chemokines and cytokines, including tumour necrosis factor (TNF)-α, IP-10/CXCK10, MIG/CXCL9, monocyte chemoattractant protein 1 (MCP-1)/CCL2 and macrophage inflammatory protein 1α (MIP-1α)/CCL3, were elevated in the early phase of infection in the lungs of WT mice." (PMID 36243815, 2022).
infection (continued). "Cytokines in the brain (TNF-α, CCL-2, CXCL-2, CXCL-10, IL-1β, IL-6, IL-17, and M-CSF) were upregulated after infection at 3 dpi, and the cytokine content gradually decreased with extension of the infection time." (PMID 36352407, 2022). "Notably, we found that the expression of specific markers of M1 type microglia (Aif1, Cd86, Cd40, Ccl2, Ccr2, Cx3cr1, IL-1β, IL-6, and NOS2) was elevated post infection." (PMID 36618398, 2022). "The cytokines retrieved from M9809 gene set of Molecular Signatures Database in Gene Set Enrichment Analysis (GSEA), such as IL-7, CCL2, CXCL10 and IFNs, were significantly up-regulated in cerebral cortex, but markedly down-regulated in cerebellum and right ventricle post infection." (PMID 35377064, 2022). "Compared to virulent MERS-CoV-MA-WT and MERS-CoV-MA-mNLS infection, attenuated MERS-CoV-MA-Δ4b induced, either at 4 or 6 dpi, lower levels of CCL2, CCL4 and CXCL10, which are monocyte and macrophage chemoattractants, and CXCL1 and CXCL2, which are neutrophil chemoattractants." (PMID 36129908, 2022). "We speculate that CCL2 and CCL7 produced by lung AECIIs upon VACV∆C7L infection are likely to be involved in the recruitment of CCR2+Ly6C+ monocytes into the infected areas in the lungs." (PMID 35351885, 2022). "Increased concentrations of CCL2/MCP-1 and CXCL10/IP-10 resulted in an augmented recruitment of monocytes to infection sites and, consequently, might generate cells more susceptible to CHIKV infection." (PMID 35456119, 2022). "Chemokine (C-C-motif) ligand 2 (CCL2), also known as monocyte chemoattractant protein-1 (MCP-1), is a member of the chemokine family, and responsible for attracting leukocytes to sites of infection or injury to mediate defense and repair." (PMID 35037831, 2022). "We, therefore, quantified SC mRNA levels encoding various pro-inflammatory and disease resolving factors, namely, the monocyte chemoattractant CCL2, TNF, IFNγ, a prominent mediator of MHV virus control, iNOS, IL10 and arginase 1 (Arg1) over the course of infection." (PMID 36333761, 2022). "T. denticola single species implant infections systemically increased IL-6, IL-13, CXCL1/KC, CCL-3/MIP1α, and CCL2/MCP compared to tissue infection without the implant." (PMID 35203495, 2022). "In addition to IL-6, CXCL1 and CCL2, IL-1β protein levels in PGRN KO kidney were also significantly lower than WT mice at day 9 post-infection when significantly lower fungal burden was observed in PGRN KO mice." (PMID 36121866, 2022). "There was also a reduced immune response to infection, which was characterized by lower levels of neutrophil and macrophage infiltration in the lung, and lower levels of cytokines IFN-γ, IL-1β, IL-6, TNF-α, IL-10, IL-12, IP-10, and chemokine CCL2." (PMID 35204727, 2022). "The increased release of TNF-α, IL-23, CCL2, CXCL8, and CXCL10 by sc1o-treated MdMs may contribute to a pro-inflammatory environment at the infection site and thereby promote the immune response against pathogens via several mechanisms." (PMID 33330947, 2021). "Along with this observation, we also observed significantly lower levels of IL-6, IFN-γ, and CXCL-10 24 h post-infection, IL-17A and TNF-α 4 days post-infection, and IL-1β, CCL2 and CCL5 7 days post-infection in the lung of IL-38-treated mice, compared with mice without IL-38 administration." (PMID 33414457, 2021). "In the brainstem, it was observed an increase of pro-inflammatory cytokines, such as IL-1β, IL-12(p70), IL-13, and TNF-α; chemokines, such as CCL2, CCL3, CCL4, CCL11, CXCL10, and CXCL1; growth factors, such as G-CSF, GM-CSF, M-CSF, and anti-inflammatory IL-10 at ten days post-infection." (PMID 33917837, 2021). "However, upon comparing the chemokine profile of the three hCoVs, it can be concluded that CCL2/MCP-1, CXCL8, and CXCL10/IP10 have vital roles in the pathogenesis of infection and serve as prognostic markers for hCoVs’ severity." (PMID 34046036, 2021).